PTTG1 (PTTG1 regulator of sister chromatid separation, securin)
Diseases named in the same sentence as PTTG1 in open-access papers (continued):
Sharing a sentence is not in itself a finding about the gene and the disease.
COVID-19 (4 papers, 2021 to 2023). A disease caused by infection with severe acute respiratory syndrome coronavirus 2. "The results showed that the interaction relationship between EZH2 and PTTG1 was the strongest in the COVID-19 dataset, and the expression was positively correlated." (PMID 37335738, 2023). "Genes involved in cell cycle, were over-expressed among COVID-19 compared to both HLTY controls and INFL, with a “hill” pattern (e.g. PTTG1, CDC6, MAD2L1, E2F1)." (PMID 34135895, 2021). "In the study of tissue regeneration after acute injury, we analyzed the database of ALF and COVID-19 by bioinformatics method and found common hub genes, including CDC20, CENPF, KIF4, KIF11, NUSAP1, TPX2, and PTTG1, which were related to mitosis and cell cycle regulation." (PMID 36911196, 2023).
esophageal cancer (4 papers, 2015 to 2022). A primary or metastatic malignant neoplasm involving the esophagus. "The PPI results of the first five KEGG pathway proteins showed that UBE2C mainly influenced the biological function of esophageal cancer by synergistic effects with CDK1, PTTG1, and SKP2 (all three are involved in the cell cycle pathway)." (PMID 34488675, 2021). "Pathway anaylsis showed that UBE2C mainly influenced the biological function of esophageal cancer by synergistic effects with CDK1, PTTG1 and SKP2." (PMID 34488675, 2021).
gastric cancer (4 papers, 2018 to 2026). A primary or metastatic malignant neoplasm involving the stomach. "An association of Securin/PTTG1 upregulation and gastric cancer in human was also demonstrated earlier." (PMID 35033090, 2022). "Moreover, association of Securin/PTTG1 upregulation and gastric cancer in human was also demonstrated." (PMID 35033090, 2022).
lymphoma (4 papers, 2006 to 2018). A malignant (clonal) proliferation of B- lymphocytes or T- lymphocytes which involves the lymph nodes, bone marrow and/or extranodal sites. "Moreover, PTTG1 overexpression was detected in many histological subtypes of lymphoma." (PMID 29649138, 2018).
somatotroph adenomas (4 papers, 2019 to 2022). "Second, miR-423-5p, which targets PTTG1, shows decreased expression in somatotroph adenomas, and inhibits the expression of PTTG1 at both the mRNA and protein levels." (PMID 33574795, 2020). "Proteomics data indicated the protein levels were 2.16-fold higher for SYT1 and 4.96-fold higher for PTTG1 in somatotroph adenomas than in healthy pituitary glands." (PMID 31391849, 2019). "PTTG1 were targets of miR-423-5p and acted as potential biomarkers for somatotroph adenoma therapeutic interventions through gene therapy." (PMID 31391849, 2019). "Western blots showed protein levels of 0.43 ± 0.15-fold for SYT1 and 0.23 ± 0.14-fold for PTTG1 in somatotroph adenomas compared to the control group and restored to 0.78 ± 0.3-fold and 0.94 ± 0.15-fold in miR-423-5p+inhibitor group (p< 0.05)." (PMID 31391849, 2019). "H-Scores were 223.1 ± 34.7 for PTTG1 and 163.4 ± 42.3 for SYT1 in 62 somatotroph adenomas specimens and 84.2 ± 21.3 for PTTG1 and 47.4 ± 17.2 for SYT1 in 10 healthy pituitary specimens by IHC." (PMID 31391849, 2019). "In our study, mRNA and proteomics profiling showed that PTTG1 was highly expressed in somatotroph adenomas compared to healthy pituitary glands." (PMID 31391849, 2019). "H-scores were 223.1 ± 34.7 for PTTG1 and 163.4 ± 42.3 for SYT1 in 62 somatotroph adenomas specimens and 84.2 ± 21.3 for PTTG1 and 47.4 ± 17.2 for SYT1 in 6 healthy pituitary specimens by IHC." (PMID 31391849, 2019). "Microarray analysis showed that mRNA levels were 12.17-fold higher for SYT1 and 2.41-fold higher for PTTG1 in somatotroph adenomas than in healthy pituitary glands." (PMID 31391849, 2019). "Additionally, whole genomic regions of seven genes (HMGA2, FGFR4, PTTG1, RB1, GNAS, AIP, GPR101) associated with acromegaly were added to the profiling target." (PMID 34400688, 2021). "Somatotroph adenomas with recurrent aneuploidy have relatively high expression of PTTG1; as a regulator of sister chromatid segregation, this may subsequently drive chromosomal instability." (PMID 33574795, 2020). "High expression of PTTG1 in somatotroph adenomas may be one of the reasons for promoting cell migration and proliferation." (PMID 31391849, 2019). "Integrating the transcriptomics and proteomics profiling of somatotroph adenomas, we revealed PTTG1 and SYT1 were differently expressed at the protein and mRNA levels between somatotroph adenomas and healthy pituitary samples; these two genes were the targets of miRNA-423-5p." (PMID 31391849, 2019). "PTTG1 may act as biomarkers for clinical treatment of somatotroph adenomas." (PMID 31391849, 2019). "RT-PCR result showed the mRNA levels of PTTG1 and SYT1 in somatotroph adenomas samples were higher than those in healthy pituitary glands." (PMID 31391849, 2019). "IHC was used to analyze the H-scores of PTTG1 and SYT1 for 62 somatotroph adenomas and 6 healthy pituitary samples." (PMID 31391849, 2019). "PTTG1 and SYT1 were the target mRNAs of miR-423-5p, and transcriptomics and proteomics profile both indicated the high expression of PTTG1 and SYT1 in somatotroph adenomas." (PMID 31391849, 2019).
squamous cell carcinoma (4 papers, 2006 to 2020). A carcinoma arising from squamous epithelial cells. "Hence, the observed increase of PTTG1 on the mRNA and protein level suggests a similar function of this protein in invasive squamous carcinomas." (PMID 28073359, 2017). "Firstly, the expression levels of PTTG3P and two other members of the PTTG family, PTTG1 and PTTG2, were analyzed across twenty-four different cancers, including squamous cell carcinomas, adenocarcinomas and other cancers based on data from the UALCAN database." (PMID 32824814, 2020).
cholangiocarcinoma (3 papers, 2020 to 2021). A carcinoma that arises from the intrahepatic biliary tree (intrahepatic cholangiocarcinoma) or from the junction, or adjacent to the junction, of the right and left hepatic ducts (hilar cholangiocarcinoma). "Silencing of PTTG1 inhibits cell proliferation and inhibits cyclin D1 expression in cholangiocarcinoma cells." (PMID 33061798, 2020). "However, CD36, GGCX, UBASH3B, DBN1, PTTG1, CCNA2, and SPATS2 are found in other tumors to regulate tumor progression, which may also regulate cholangiocarcinoma progression and affect the recurrence of CCA." (PMID 32071556, 2020).
colorectal tumor (3 papers, 2005 to 2024). "PTTG1 is an oncogene in several types of human cancers, an independent poor prognostic factor for patients with colorectal tumor." (PMID 38725628, 2024). "A correlation between the levels of expression of PTTG1 with increased tumor invasiveness and with the degree of malignancy has been demonstrated in pituitary and colorectal tumors." (PMID 15649325, 2005).
laryngeal carcinoma (3 papers, 2021 to 2024). Carcinoma that arises from the laryngeal epithelium. "The expression of PTTG1 showed a significant correlation with cell proliferation in laryngeal cancer patients." (PMID 39139816, 2024). "For example, PTTG1 is overexpressed in laryngeal cancer, and predicts a poorer overall survival rate of patients with laryngeal cancer." (PMID 34025420, 2021). "PTTG1 expression was significantly correlated with lymph node metastasis, clinical stage, and degree of tumor differentiation in patients with laryngeal cancer." (PMID 33845847, 2021).
meningioma (3 papers, 2016 to 2025). A generally slow growing tumor attached to the dura mater. "For example, in meningiomas, PTTG1 immunoreactivity closely parallels Ki-67 and is associated with higher tumor grade and proliferation rate." (PMID 41573212, 2025). "In meningiomas, PTTG1 shows similar results as Ki-67 for identifying higher grade tumors and can be a useful marker to identify patients with a higher risk." (PMID 41573212, 2025). "Up to date, one descriptive study showed a PTTG1 protein expression in most meningioma tissues and an expression variability among different subtypes without analysis of clinical prognosis." (PMID 26894859, 2016). "In WHO°II meningiomas reduced expression of LEPR and MN1 resulted in a significantly shorter PFS, while in WHO°III meningiomas this was the case for a higher expression levels of PTTG1 and UBE2C." (PMID 26894859, 2016). "Moreover in a couple of cancer entities other than meningioma PTTG1 has been shown to be involved in tumor progression and to be correlated with poor prognosis." (PMID 26894859, 2016). "Among these, PTTG1 and LEPR showed a significant association with recurrence independent of known prognostic confounders such as WHO grade and therefore might serve in the future as novel putative biomarkers to predict aggressiveness of meningiomas." (PMID 26894859, 2016). "Moreover, multivariate survival analysis established increased PTTG1 and decreased LEPR expression as novel and potentially powerful prognostic markers for the identification of clinically aggressive meningiomas." (PMID 26894859, 2016).
ovarian tumors (3 papers, 2006 to 2012). "PTTG1 is found to be overexpressed in most of the ovarian tumors analyzed to date and the PTTG1 promoter is specifically activated in tumor cells, including OSE tumor cells." (PMID 19014669, 2008).
papillary renal cell carcinoma (3 papers, 2019 to 2022). A rare subtype of renal cell carcinoma, arising from the renal tubular epithelium and showing a papillary growth pattern, which typically manifests with hematuria, flank pain, palpable abdominal mass or nonspecific symptoms, such as fatigue, weight loss or fever. "We identified 5 mRNAs that are associated with the survival of patients with papillary renal cell carcinoma,namely CCNB2, IGF2BP3, KIF18A, PTTG1, and BUB1 in the training set." (PMID 30822312, 2019). "Moreover, a high expression level of PTTG1 was correlated to the immune checkpoint response in the papillary renal cell carcinoma cohort." (PMID 35768832, 2022). "In general, the 5-mRNA (CCNB2, IGF2BP3, KIF18A, PTTG1, and BUB1) were identified and validated, which can predict papillary renal cell carcinoma patient survival." (PMID 30822312, 2019).
renal cell carcinoma (3 papers, 2021 to 2025). "The upregulation of the oncogene Pttg1 in Smarca4-deficient kidneys may shed new light on therapeutic strategies for renal cell carcinoma resulting from SWI/SNF complex deficiency." (PMID 37727504, 2023). "One partner gene of ESPL1, PTTG1, was proved to be an oncogene in renal cell carcinoma and other cancer types." (PMID 34856998, 2021).
sarcoma (3 papers, 2012 to 2022). A usually aggressive malignant neoplasm of the soft tissue or bone. "In summary, here we demonstrate that ISG15, NUP50, PTTG1, SERPINE1, and TSR1 are highly expressed in sarcoma tissues and associated with sarcoma metastasis and poor prognosis." (PMID 33123466, 2020). "The results of immunohistochemistry indicated that SG15, NUP50, PTTG1, SERPINE1, and TSR1 were highly expressed in sarcoma tissues." (PMID 33123466, 2020). "The results of qRT-PCR suggested that ISG15, NUP50, PTTG1, SERPINE1, and TSR1 were highly expressed in sarcoma tissues." (PMID 33123466, 2020). "To validate whether ISG15, NUP50, PTTG1, SERPINE1, and TSR1 are differentially expressed in sarcoma tissues, we experimentally validated their expression in the tissues of 10 sarcoma patients." (PMID 33123466, 2020). "PTTG1 expression in ACC, BRCA, lymphoid neoplasm diffuse large B-cell lymphoma (DLBC), ovarian serous cystadenocarcinoma (OV), PAAD, skin cutaneous melanoma (SKCM), THYM, uterine carcinosarcoma (UCS), and sarcoma (SARC) was higher than that in normal tissues (all p < 0.01)." (PMID 35281830, 2022). "Taken together, results of these experiments suggest that high expression levels of ISG15, NUP50, PTTG1, SERPINE1, and TSR1 exert a positive regulatory effect on metastasis, suggesting poor prognosis, and that Tanespimycin may effectively treat LMS sarcoma subtype." (PMID 33123466, 2020).
somatotropinomas (3 papers, 2007 to 2018). "We also measured two well-known proliferation markers in our cohort of somatotropinoma samples, and found that PTTG1 mRNA levels were higher than Ki67 levels." (PMID 29670116, 2018).
systemic lupus erythematosus (3 papers, 2013 to 2023). An autoimmune multi-organ disease typically associated with vasculopathy and autoantibody production. "Moreover, a genome-wide association study has highlighted a variant, that is, rs2431697, in an intergenic region between PTTG1 (Pituitary Tumor-Transforming 1) and miR-146a, associated with lupus susceptibility." (PMID 27635407, 2016). "It has recently been shown that the genomic region on chromosome 5, encompassing pre-miR-146a and PTTG1, is associated with systemic lupus erythematosus (SLE) and cancers, including papillary thyroid tumor." (PMID 24145614, 2013).
triple-negative breast carcinoma (3 papers, 2020 to 2023). An invasive breast carcinoma which is negative for expression of estrogen receptor (ER), progesterone receptor (PR), and human epidermal growth factor receptor 2 (HER2). "The data showed that triple-negative breast cancer cell lines, such as MDA-MB-231, had high expressions of PTTG1 and PTTG3." (PMID 33173433, 2020).
Cirrhosis (2 papers, 2019 to 2022). A chronic disorder of the liver in which liver tissue becomes scarred and is partially replaced by regenerative nodules and fibrotic tissue resulting in loss of liver function. "Pttg1 expression significantly increased in rats with severe fibrosis and reached maximum levels in rats with cirrhosis." (PMID 35050550, 2022). "Overactivation of the PTTG1/DLK1 axis in human cirrhosis was further confirmed." (PMID 35050550, 2022). "Despite overexpression of PTTG1 in liver biopsies from patients with HCC, very little data are available on its expression in preneoplastic conditions such as advanced liver fibrosis and cirrhosis." (PMID 35050550, 2022). "PTTG1 and DLK1 transcription are increased in rats and patients with hepatic cirrhosis." (PMID 35050550, 2022).
colorectal neuroendocrine tumor (2 papers, 2017 to 2025). A well differentiated, low, intermediate, or high grade neoplasm with neuroendocrine differentiation that arises from the colon or rectum. "The PTTG1 protein has been reported to be detectable in plasma of healthy subjects and patients with colorectal neuroendocrine tumor." (PMID 29371923, 2017). "Additionally, the combined expression of miR-186 and its downstream target PTTG1 (pituitary tumor-transforming 1) has shown predictive value for tumor infiltration and invasion in colorectal neuroendocrine tumors, with detection possible through non-invasive blood and stool tests." (PMID 39959663, 2025).
endocrine cancers (2 papers, 2015 to 2023). "Genes highlighted include the proto-oncogene PTTG1 found to be significantly upregulated in metastatic tumours, consistent with studies that have associated it with metastatic behaviour of endocrine and non-endocrine tumours." (PMID 38124114, 2023). "Some of the most upregulated genes in the metastatic tumours are the pituitary tumour-transforming gene (PTTG1), a marker of invasion in many tumour types including endocrine cancers and the pro-proliferative cyclin B2 CCNB2." (PMID 38124114, 2023).
fibrosis (2 papers, 2020 to 2022). the formation of excess fibrous connective tissue in an organ or tissue in a reparative or reactive process. "Overall, these results support the protective effects on hepatic function resulting from Pttg1 mRNA silencing in rats with experimental fibrosis." (PMID 35050550, 2022). "PTTG1 has also been reported to be functionally required for hepatic fibrosis progression in an animal model of chronic liver injury." (PMID 33396939, 2020). "Furthermore, Tgfßr1 and Pdgfrß expression appeared also markedly attenuated, indicating that Pttg1 silencing effectively abrogates profibrogenic activity in CCl4‐induced fibrosis." (PMID 35050550, 2022).
GH-cell adenomas (2 papers, 2011 to 2021). "In conclusion, this study proposes that c-miRNAs, especially miR-423-5p, and PTTG1 could be considered valuable biomarkers for the development of new therapeutic strategies against somatotropic adenomas." (PMID 34564317, 2021). "Further studies revealed that overexpression of PTTG1 may contribute to the promotion of proliferation and migration of somatotropic adenoma cells." (PMID 34564317, 2021).
hepatitis B (2 papers, 2021 to 2023). "Among them, PTTG1, MAD2L1, CDK1, and NEK2 may be the key prognostic genes of the hepatitis B inflammation and cancer transformation." (PMID 34539726, 2021).
liposarcoma (2 papers, 2007 to 2025). A usually painless malignant tumor that arises from adipose tissue. "To ensure the broader applicability of LEP and PTTG1 as classification biomarkers, we performed an independent validation using an external liposarcoma cohort (GSE30929)." (PMID 40407808, 2025). "The external dataset’s alignment with our findings underscores the potential of LEP and PTTG1 as reproducible biomarkers for prognosis and therapeutic stratification in liposarcoma." (PMID 40407808, 2025). "Genes highly expressed in the dedifferentiated/pleomorphic liposarcomas included cell-cycle genes like CCNA2, CCNB2, CDC2, KIFC1, KIF23 and PTTG1, motility genes like AMFR, ANXA1, CKB, CNN2 and FN1 and homeostasis-related genes." (PMID 17359542, 2007).
liver diseases (2 papers, 2022). "PTTG1 is involved in fibrotic extracellular matrix remodeling and its silencing decreases portal hypertension and alliviates fibrosis progresion." (PMID 35050550, 2022). "In summary, there are compelling data strongly suggesting that dysregulation of the PTTG1/DLK1 axis is involved in the pathogenesis of fat metabolism in liver diseases." (PMID 35805898, 2022). "In line, Pttg1 siRNA also showed significantly reduced portal hypertension than fibrotic animals receiving C− siRNA." (PMID 35050550, 2022). "This investigation aimed to explore whether PTTG1/DLK1 signalling contributes to the activation of the fibroproliferative process in liver disease." (PMID 35050550, 2022). "For all these reasons, PTTG1/DLK1 axis could be of major importance in the pathogenesis of liver diseases." (PMID 35805898, 2022). "Given this background, we aimed to explore the hypothesis that PTTG1/DLK1 signalling should play a central role in the activation of the fibrogenic process in liver disease." (PMID 35050550, 2022). "The present article intends to extensively review the major mechanisms regulating synthesis, secretion, and maturation of PTTG1 and DLK1, as well as the principal evidence pointing to these peptides as possible antifibrogenic targets for the treatment of advanced liver disease." (PMID 35805898, 2022). "Pttg1 gene silencing normalizes expression of Dlk1, arrests activation of HSC, diminishes expression of ECM‐related genes and finally decreases hepatic collagen deposition and reduces portal hypertension." (PMID 35050550, 2022).